KRTAP9-3 (keratin associated protein 9-3)
Description:
In the hair cortex, hair keratin intermediate filaments are embedded in an interfilamentous matrix, consisting of hair keratin-associated proteins (KRTAP), which are essential for the formation of a rigid and resistant hair shaft through their extensive disulfide bond cross-linking with abundant cysteine residues of hair keratins. The matrix proteins include the high-sulfur and high-glycine-tyrosine keratins.
Synonyms: KAP9.3; KRTAP9.3
Tractability: No criterion of Open Targets' tractability assessment is met for any kind of drug.
Gene: Protein-coding gene on chromosome 17 (41,232,449 to 41,233,454, forward strand). Ensembl gene ENSG00000204873.
Pathways (Reactome):
Developmental Biology: Keratinization
Gene Ontology:
Molecular function: identical protein binding; protein binding
Cellular component: cytosol; keratin filament
Genetic constraint (gnomAD): Loss-of-function variants: 12 observed, 12.81 expected, observed/expected ratio (o/e) 0.94, 90% interval 0.6 to 1.51. The upper end of that interval is the gene's LOEUF score, 1.51, which puts it in group 6 of 6, group 1 being the genes least tolerant of losing a copy. Missense variants: 232 observed, 196.67 expected, observed/expected ratio (o/e) 1.18, 90% interval 1.06 to 1.32. Synonymous variants: 89 observed, 69.37 expected, observed/expected ratio (o/e) 1.28, 90% interval 1.08 to 1.53.
Homologues: Orthologues: chimpanzee KRTAP9-3 (97% identical). Paralogues in human: KRTAP9-2 (96% identical), KRTAP9-7 (93% identical), KRTAP9-8 (93% identical), KRTAP9-9 (93% identical), KRTAP9-4 (87% identical), KRTAP9-6 (84% identical), KRTAP9-1 (79% identical), KRTAP4-12 (52% identical), KRTAP4-6 (50% identical), KRTAP4-9 (48% identical), KRTAP4-11 (47% identical), KRTAP4-4 (45% identical), and 35 more.